DNMT3B (DNA methyltransferase 3 beta)
Diseases named in the same sentence as DNMT3B in open-access papers (continued):
Sharing a sentence is not in itself a finding about the gene and the disease.
endometrial adenocarcinoma (1 paper, 2016). "For example, estrogen was reported to increase DNMT3b expression in endometrial adenocarcinoma cells, but decrease DNMT3b transcription in an endometrial explant culture." (PMID 26980709, 2016).
germinoma (1 paper, 2011). A malignant germ cell tumor arising in the central nervous system. "DNMT3B was generally expressed at levels 4–16-fold greater in the YST samples analysed compared with the germinoma samples." (PMID 21712824, 2011). "Indeed, analysis of the array data on the same cohort of GCTs revealed that DNMT3B was more strongly expressed in YSTs than in germinomas (LOD scores of 3.36 and 6.7, respectively, P=0.0006)." (PMID 21712824, 2011). "Although we had access to only a small number of RNA samples from the same tumours analysed for their methylation status, our data did reveal a significant difference between germinomas and YSTs in the level of expression of DNMT3B, but not EZH2 or SUZ12 (data not shown)." (PMID 21712824, 2011).
HCMV infection (1 paper, 2024). "It was observed that HCMV infection resulted in the re-localization of DNMT1 and DNMT3B from the nucleus in the cytoplasm." (PMID 38314203, 2024).
Hepatitis (1 paper, 2020). Inflammation of the liver. "In contrast, TAA-induced hepatitis considerably changed the gene expression profile in the Dnmt3b-deficient liver by inducing significant enrichment in 21 gene sets." (PMID 33277576, 2020). "To explore the role of Dnmt3b in the liver tissue under chronic inflammation, we induced hepatitis in Dnmt3b-deficient mice by adding 0.02% thioacetamide (TAA) in drinking water for four weeks and collected the liver tissues for further examination." (PMID 33277576, 2020). "The presence of several Ki67-positive cells in the inflammatory liver tissue in Dnmt3b-deficient mice suggested that the tissue regeneration and cell proliferation was promoted by the exacerbation of hepatitis." (PMID 33277576, 2020). "The present findings indicate that TAA treatment increased mitochondrial dysfunction and ROS production in the hepatocytes of Dnmt3b-deficient mice, leading to the exacerbation of hepatitis." (PMID 33277576, 2020). "Remarkably, the Dnmt3b-deficient mouse liver showed severe hepatitis especially around the Glisson sheath as compared to the liver of Dnmt3b-wild type (WT) mice, with massive infiltration of macrophages as well as the increased recruitment of neutrophils and lymphocytes." (PMID 33277576, 2020). "To elucidate molecular pathways involved in hepatitis and hepatocarcinogenesis that are enhanced by Dnmt3b depletion, we performed gene set enrichment analysis (GSEA) using RNAseq data." (PMID 33277576, 2020). "We have generated a novel mouse model in which the Dnmt3b gene is specifically deleted in hepatocytes and have revealed that DNMT3B plays an important role in protecting the liver tissue from the exacerbation of hepatitis and hepatocarcinogenesis." (PMID 33277576, 2020).
Hypertension (1 paper, 2022). The presence of chronic increased pressure in the systemic arterial system. "WT rats exposed to SU/Hx/Nx developed hypertension and exhibited increased DNMT activity and Dnmt1 and Dnmt3b expression." (PMID 36372233, 2022).
intestinal tumors (1 paper, 2012). "In mouse models, it has been shown that heterozygous mutations for Dnmt1 cause a global reduction in DNA methylation, which was associated with a reduced prevalence of intestinal tumors, whereas deletion of Dnmt3b led to reduced tumor size." (PMID 23284304, 2012). "Consistent with its tumor promoting role, overexpression of Dnmt3b was shown to enhance intestinal tumor formation, which was accompanied by the emergence of methylation patterns that were similar to those usually observed in human colon cancers." (PMID 23284304, 2012).
Kaposi's sarcoma (1 paper, 2021). A malignant neoplasm characterized by a vascular proliferation which usually contains blunt endothelial cells. "DNMT1 and DNMT3B are involved in Kaposi’s sarcoma, and DNMTs are upregulated in leiomyosarcoma." (PMID 35008848, 2021).
kidney papillary carcinoma (1 paper, 2025). "Finally, in kidney papillary carcinoma (KIRP), the signature included YTHDC2, IGF2BP2, DNMT3B, TRMT6, HNRNPC, and NSUN5." (PMID 40565233, 2025).
knee osteoarthritis (1 paper, 2022). "A matched case-control study showed that DNMT1, DNMT3A, and DNMT3B gene polymorphisms are significantly associated with radioactive primary knee osteoarthritis." (PMID 35747513, 2022).
leukoplakia (1 paper, 2021). A white patch or plaque on a mucous membrane that cannot be characterized clinically or pathologically as any other disease. "The expression of three m5C regulators—NOP2, DNMT3B, and ALYREF—was upregulated in oral leukoplakia patients from two microarray datasets, GSE26549 and GSE85195." (PMID 34957065, 2021).
liver cirrhosis (1 paper, 2020). "Masson trichrome staining clearly shows a significant increase in bridging fibrosis in the Dnmt3b-deficient liver, indicating the progression of liver cirrhosis." (PMID 33277576, 2020).
malignant glioma (1 paper, 2011). A grade III or grade IV glioma arising from the central nervous system. "Taken together, the significant upregulation of DNMT1 and DNMT3b indicates theirinvolvement in CGI methylation processes in malignant glioma." (PMID 21365007, 2011). "In the current study, we show that in malignant glioma DNMT1 and DNMT3b weresignificantly upregulated, as compared to normal brain." (PMID 21365007, 2011).
melasma (1 paper, 2019). "At the end of treatment, all three groups showed improvement in melasma and reduction in DNMT1 and DNMT3b." (PMID 31143777, 2019).
monocytic leukemia (1 paper, 2019). "In established HMA-resistant cell lines from a human monocytic leukemia cell line (MOLM-13), protein levels of DNMT3B were found upregulated compared to parental cell line and mRNA expression of DNMT1 and DNMT3A in HMA-resistant cell lines decreased compared to parental cell line." (PMID 31331399, 2019).
mucositis (1 paper, 2023). Mucositis is inflammation and damage of the mucous membranes lining the mouth and other parts of the gastrointestinal (GI) tract. "We conclude that the DNMT1 methylation profile is associated with the post-mucositis period and that the genetic and epigenetic profiles of DNMT3A and DNMT3B are associated with creatinine levels." (PMID 37372315, 2023).
multiple sclerosis (1 paper, 2019). A progressive autoimmune disorder affecting the central nervous system resulting in demyelination. "The present investigation aimed to explore the association of DNMT3B-579G>T (rs1569686) polymorphism with multiple sclerosis (MS)." (PMID 31565203, 2019).
Myasthenia (1 paper, 2013). "DNMT3B -579G>T allele frequencies in Myasthenia Gravis patients and Controls." (PMID 24260492, 2013). "DNMT3B -579G>T genotype frequencies in Myasthenia Gravis patients and Controls." (PMID 24260492, 2013).
myeloid leukemia (1 paper, 2023). A clonal proliferation of myeloid cells and their precursors in the bone marrow, peripheral blood, and spleen. "Aberrant DNA methylation mediated by mutations of TET2, WT1, DNMT1, DNMT3A, and DNMT3B genes is correlated to the pathogenesis of myeloid leukemia." (PMID 37375831, 2023).
nicotine dependence (1 paper, 2023). Physical and psychological dependence on nicotine. "The value of studying smoking effects against an identical genetic background is clear if one considers that one of the most strongly associated genetic variants for nicotine dependence is located in the DNA methyltransferase gene DNMT3B." (PMID 37643467, 2023).
odontogenic tumor (1 paper, 2021). "However, the mean nuclear positivity for DNMT1, DNMT3A, DNMT3B, and H3K9ac, were, respectively, 65.07, 82.03, 39.56, and 88.37%, representing the first report of these proteins in a malignant odontogenic tumor." (PMID 35048062, 2021).
osteoporosis (1 paper, 2021). A condition of reduced bone mass, with decreased cortical thickness and a decrease in the number and size of the trabeculae of cancellous bone (but normal chemical composition), resulting in increased fracture incidence. "miR-29a reversed FoxO3 loss to improve senescence program through targeting Dnmt3b-mediated FoxO3 methylation and increased antioxidant proteins, including Oxr1, to downregulate oxidative stress and DNA methylation, compromising age-induced osteoblast loss and osteoporosis." (PMID 34439496, 2021).
overnutrition (1 paper, 2021). An imbalanced nutritional status resulting from excessive intake of nutrients. "A significant effect of maternal overnutrition was evident for DNMT1 and DNMT3B expression in the AC of day-28 conceptuses." (PMID 34573470, 2021).
penile cancer (1 paper, 2017). A primary or metastatic malignant neoplasm that affects the penis. "In addition to the potential driver genes herein described, shorter overall survival was associated with BIRC5 and DNMT3B overexpression (log-rank test, P = 0.026 and P = 0.002, respectively) highlighting its potential as novel prognostic marker for penile cancer." (PMID 28751665, 2017).
pituitary tumor (1 paper, 2015). A benign or malignant neoplasm affecting the pituitary gland. "DNMT3B has been reported to be over expressed in pituitary tumors." (PMID 26509893, 2015).
PN tumors (1 paper, 2021). "Furthermore, based on the N-Myc ChIP-seq data, we found that N-Myc binding was enhanced at the promoters of Dnmt1, Dnmt3b, and Mdb4 in PRN (primarily poorly differentiated histology) compared to PN tumors (primarily adenocarcinoma histology)." (PMID 34099734, 2021).
pneumoconiosis (1 paper, 2022). An occupational lung disorder caused by inhalation of dust particles.
prostate adenocarcinoma (1 paper, 2023). "In silico RNA sequencing of prostate adenocarcinoma (PRAD) TCGA analysis demonstrated upregulation of DNMT3B, DNMT1, and MBD2 in tumors (n = 497) compared to normal (n = 52) samples, suggesting a global increase in DNA methylation, which might be associated with gene-specific downregulation." (PMID 38201944, 2023).
psychosis (1 paper, 2021). "We found an increase in DNMT3B expression in both BD and SZ, implicating its possible role in psychosis." (PMID 33875800, 2021). "Specific and increased expression of DNMT3B was also found in the PFC of SZ patients, suggesting that DNMT3B is involved in altered DNA methylation in psychosis." (PMID 33875800, 2021).
pterygium (1 paper, 2022). A wedge-shaped fibrovascular lesion arising from the bulbar conjunctiva and extending to the cornea. "Furthermore, we have found that the expression of multiple epigenetic regulators was upregulated in the 3D pterygium model, including DNA methyltransferase DNMT3B, lysine demethylase KDM6B, and histone deacetylase HDAC5." (PMID 35101743, 2022).
rectal cancer (1 paper, 2020). A primary or metastatic malignant neoplasm that affects the rectum. "Furthermore, a cooperation between DNMT1 and DNMT3B was observed in humans; when disrupted, DNA methylation was decrease by 95% in colon rectal cancer cell." (PMID 32614880, 2020).
recurrent disease (1 paper, 2025). "In this study, the associations between methylation markers (DNMT1, DNMT3A, and DNMT3B) and both locoregional recurrent disease and disease-specific mortality in patients with locally advanced LSCC treated with definitive, curatively intended radiotherapy alone was investigated." (PMID 40507223, 2025).
renal fibrosis (1 paper, 2025). A final common manifestation of a wide variety of chronic kidney diseases characterized by glomerulosclerosis and tubulointerstitial fibrosis. "Thus, our study demonstrated that the aberrant expression of DNMT3B induced by high glucose and the resulting suppression of SFRP5 contribute to renal fibrosis, revealing a novel role of DNMT3B in the pathogenesis of DKD." (PMID 40595027, 2025).
Respiratory tract infection (1 paper, 2021). An infection of the upper or lower respiratory tract. "This also holds true for further studies on the use of flagellin, administered via the airways as a possible immune enhancing strategy in the treatment of respiratory tract infections, and the role of Dnmt3b herein." (PMID 33793661, 2021).
Right ventricular hypertrophy (1 paper, 2023). In this case the right ventricle is more muscular than normal, causing a characteristic boot-shaped (coeur-en-sabot) appearance as seen on anterior- posterior chest x-rays. "Overexpression of DNMT3B was also found to transcriptionally regulate inflammatory pathways, and could attenuate hypoxia-induced PH and right ventricular hypertrophy in mice, demonstrating the therapeutic potential of upregulating DNMT3B in the treatment of PH." (PMID 37947606, 2023).
soft tissue sarcoma (1 paper, 2016). A malignant neoplasm arising from muscle tissue, adipose tissue, blood vessels, fibrous tissue, or other supportive tissues excluding the bones. "Understanding the molecular mechanisms associated with the activated muscular differentiation after DNMT3B depletion is essential to design novel pharmacological treatments for this soft tissue sarcoma." (PMID 27764816, 2016).
squamous cell carcinoma (1 paper, 2017). A carcinoma arising from squamous epithelial cells. "Altogether, we demonstrate that Dnmt3a and Dnmt3b protect the epidermis from tumorigenesis and that squamous carcinomas are sensitive to inhibition of PPAR-γ." (PMID 28425913, 2017). "Only upon combined deletion of Dnmt3a and Dnmt3b, squamous carcinomas become more aggressive and metastatic." (PMID 28425913, 2017). "Although these differences were similar to the ones observed in single Dnmt3a-cKO mice, DcKO mice formed aggressive squamous cell carcinomas at a higher frequency as compared to the single cKOs of Dnmt3a or Dnmt3b." (PMID 28425913, 2017). "However, both Dnmt3a and Dnmt3b repress the malignant transformation of epidermal cells into aggressive squamous cell carcinomas." (PMID 28425913, 2017).
systemic sclerosis (1 paper, 2015). A chronic disorder, possibly autoimmune, marked by excessive production of collagen which results in hardening and thickening of body tissues. "Although one might expect an increase in DNMT3a or DNMT3b to be primarily involved in initiating pro-fibrotic DNA methylation patterns, studies in the liver, lung, heart, kidneys and systemic sclerosis have implicated a role for elevated DNMT1 and/or DNMT3 or DNMT3b in fibrosis." (PMID 26435749, 2015).
teratoma (1 paper, 2005). A non-seminomatous germ cell tumor characterized by the presence of various tissues which correspond to the different germinal layers (endoderm, mesoderm, and ectoderm). "The RT–PCR analysis verified the upregulation of DNMT3B in N-SEM samples, but not in the teratoma sample, suggesting that the signal originated from undifferentiated components such as EC." (PMID 15856041, 2005).
thymic neoplasm (1 paper, 2016). "To further address this issue, we analyzed DNA methylation levels of genes involved in one-carbon metabolism (MTHFR) and DNA methylation (DNMT1, DNMT3A, and DNMT3B) in blood, tumor tissue, and healthy thymic epithelial cells from MG patients that underwent a surgical resection of a thymic neoplasm." (PMID 27999265, 2016).
vitamin D deficiency (1 paper, 2016). A nutritional condition produced by a deficiency of VITAMIN D in the diet, insufficient production of vitamin D in the skin, inadequate absorption of vitamin D from the diet, or abnormal conversion of vitamin D to its bioactive metabolites. "In support of our hypotheses that maternal vitamin D deficiency leads to global dysregulation of epigenetic maintenance via disruption of epigenetic regulatory factors, we find that Dnmt3b transcript levels are upregulated in cross 1 neonatal liver from LVD group compared to CON." (PMID 27777636, 2016).
Werner syndrome (1 paper, 2011). "Furthermore, recent evidence indicates that the Werner Syndrome gene product, WRNp, localizes to the OCT4 promoter of human PSCs undergoing retinoic acid induced differentiation where it plays a role in de novo DNA methylation by recruiting DNMT3B to the OCT4 promoter." (PMID 21698279, 2011).